HNRNPK (heterogeneous nuclear ribonucleoprotein K)
Diseases named in the same sentence as HNRNPK in open-access papers (continued):
Sharing a sentence is not in itself a finding about the gene and the disease.
colorectal adenocarcinoma (2 papers, 2006 to 2022). The most common type of colorectal carcinoma. "Collectively, high expressions of hnRNPA1, hnRNPK, hnRNPR, and hnRNPU were significantly associated with better OS rates for colorectal adenocarcinoma patients." (PMID 35875075, 2022). "Moreover, from the survival analysis results in HPA and GEPIA webtools, only hnRNPK was associated with better OS rates for colorectal adenocarcinoma patients." (PMID 35875075, 2022). "Furthermore, we demonstrated that high expressions of hnRNPA1, hnRNPK, hnRNPR, and hnRNPU were associated with better overall survival rates for colorectal adenocarcinoma patients." (PMID 35875075, 2022). "Our results illustrated that the elevated levels of hnRNPK/A1/R/U in colorectal adenocarcinoma tissues exert critical roles in the tumorigenesis of colorectal adenocarcinoma." (PMID 35875075, 2022). "The GO analysis results showed that transcription, translation, and ribosomal large subunit assembly were significantly regulated by the hnRNPK/A1/R/U alterations in colorectal adenocarcinoma." (PMID 35875075, 2022). "The interaction between hnRNPK and hnRNPA1/R/U proteins was confirmed by Co-IP in HCT116 cells, ascertaining the existence of hnRNPK/A1/R/U complex in colorectal adenocarcinoma cells." (PMID 35875075, 2022). "The results showed that hnRNPA1, hnRNPK, hnRNPR, and hnRNPU in the nucleus had higher expressions in colorectal adenocarcinoma cells compared with FHC cells." (PMID 35875075, 2022). "Our results suggested that hnRNPK was a favorable factor against human colorectal adenocarcinoma, promoting immune cell infiltration and inhibiting tumor growth." (PMID 35875075, 2022). "Our findings illustrate that the hnRNPK/A1/R/U complex is a favorable prognostic biomarker for human colorectal adenocarcinoma." (PMID 35875075, 2022). "Immunohistochemical staining revealed that hnRNPA1, hnRNPA2B1, hnRNPC, hnRNPK, hnRNPR, and hnRNPU are overexpressed in colorectal adenocarcinoma." (PMID 35875075, 2022). "Exploring the proliferation regulation mechanism of hnRNPK in colorectal adenocarcinoma was imperative." (PMID 35875075, 2022). "The relationship between hnRNPK expression and infiltration of six immune cell types was analyzed to estimate the effect of hnRNPK on the colorectal adenocarcinoma microenvironment." (PMID 35875075, 2022). "Through proliferation test, we preliminarily identified that hnRNPK was a favorable factor against human colorectal adenocarcinoma and promoted immune infiltration, thus inhibiting tumor growth." (PMID 35875075, 2022). "Targeting hnRNPK during transcription and translation could be a promising therapeutic strategy for colorectal adenocarcinoma treatment." (PMID 35875075, 2022). "Finally, through establishment of stable cell lines in vitro, we verified that hnRNPK was a favorable factor in human colorectal adenocarcinoma which promoted immune cell infiltration and inhibited tumor growth." (PMID 35875075, 2022). "Finally, through KEGG analysis, ten pathways related to the hnRNPK/A1/R/U network in colorectal adenocarcinoma were identified." (PMID 35875075, 2022). "By using IHC staining of 10 human colorectal adenocarcinoma specimens, we confirmed that hnRNPA1, hnRNPA2B1, hnRNPC, hnRNPK, hnRNPR, and hnRNPU were mainly localized in the nucleus and had higher expressions in colorectal adenocarcinoma tissues compared with adjacent normal tissues (ANT)." (PMID 35875075, 2022). "Notably, the biological functions and molecular mechanisms of hnRNPK/A1/R/U complex in colorectal adenocarcinoma still need future investigations." (PMID 35875075, 2022). "In vitro, we preliminarily investigated the role of hnRNPK in colorectal adenocarcinoma." (PMID 35875075, 2022). "Importantly, we validated that the hnRNPK/A1/R/U complex is a favorable prognostic biomarker of colorectal adenocarcinoma." (PMID 35875075, 2022).
colorectal adenocarcinoma (continued). "Targeting transcription factor hnRNPK during transcription and translation could be a promising therapeutic potential for colorectal adenocarcinoma treatment." (PMID 35875075, 2022).
endometrial cancer (2 papers, 2012 to 2024). Primary or metastatic malignant neoplasm involving the endometrium (mucous membrane that lines the endometrial cavity). "Among the proteins linked to proliferation and invasion of endometrial cancer, we identified HSPA1, TPM2, PDIA, ENO and HNRNPK." (PMID 22415234, 2012). "In addition, public database analysis revealed that HNRNPK gene expression was positively correlated with ERα gene expression but not ERβ, and the HNRNPK gene high expression group had a significantly better prognosis in endometrial cancer patients." (PMID 39246627, 2024).
epilepsy (2 papers, 2022 to 2024). A brain disorder characterized by episodes of abnormally increased neuronal discharge resulting in transient episodes of sensory or motor neurological dysfunction, or psychic dysfunction. "A smaller subgroup of pTau interactors (13 proteins) were significantly increased in epilepsy, including multiple proteins associated with regulation of mRNA splicing (HNRNPA2B1, HNRNPK, NCL)." (PMID 38289539, 2024).
metastatic cancer (2 papers, 2014 to 2021). A carcinoma which has spread from the original site of growth to another anatomic site. "In summary, our study confirms hnRNPK as a motif‐dependent exosomal miRNA‐sorting protein, that is, regulated by membrane rafts and provides initial evidence for elevated EV hnRNPK in metastatic cancers." (PMID 33931969, 2021). "Elevated EV hnRNPK in biofluids from metastatic cancer patients suggest a role as a biomarker." (PMID 33931969, 2021).
metastatic prostate carcinoma (2 papers, 2021). A carcinoma that arises from the prostate gland and has spread to other anatomic sites. "Seminal plasma EVs collected by ultracentrifugation were immunoblotted for hnRNPK from four localised prostate cancer and four metastatic prostate cancer cases." (PMID 33931969, 2021).
oral squamous cell carcinoma (2 papers, 2011 to 2023). "LINC00941 is upregulated in oral squamous cell carcinoma (OSCC) and was shown to induce epithelial-to-mesenchymal transition (EMT) in vitro by associating with the heterogeneous nuclear ribonucleoprotein K (hnRNPK)." (PMID 36869839, 2023).
retinoblastoma (2 papers, 2020 to 2023). A malignant tumor that originates in the nuclear layer of the retina. "circE2F3 bound with HNRNPK and facilitate HNRNPK-mediated mRNA stability of E2F3, improving the stability of E2F3 mRNA in retinoblastoma." (PMID 33643900, 2020).
acute promyelocytic leukemia (1 paper, 2021). An aggressive form of acute myeloid leukemia (AML), characterized by arrest of leukocyte differentiation at the promyelocyte stage, due to a specific chromosomal translocation t(15;17) in myeloid cells. "ERK inhibition or heterogeneous nuclear ribonucleoprotein K knockdown decreases cell viability, increases all‐trans retinoic acid (ATRA)‐induced differentiation in acute promyelocytic leukemia (APL) ATRA‐resistant cells, and promotes SET cleavage." (PMID 34058077, 2021).
amyotrophic lateral sclerosis (1 paper, 2023). Amyotrophic lateral sclerosis (ALS) is a neurodegenerative disease characterized by progressive muscular paralysis reflecting degeneration of motor neurons in the primary motor cortex, corticospinal tracts, brainstem and spinal cord. "In amyotrophic lateral sclerosis, hnRNPK binds to antioxidant NFE2L2 (NFE2-like BZIP transcription factor 2) and GPX1 (glutathione peroxidase 1) transcripts." (PMID 36735291, 2023).
aortic root dilatation (1 paper, 2024). "Patients with HNRNPK variants exhibited heterogeneous CHDs, including septal defects, bicuspid aortic valve with aortic root dilatation, and atrioventricular septal defect." (PMID 38667491, 2024).
apical periodontitis (1 paper, 2025). "The most credible 3-UTR candidate variants were found in TBCK (rs79409042, chromosome 4) in the phenotype Necrosis of pulp or apical periodontitis, in HNRNPK (rs696825, chromosome 9) in Pulpal and apical diseases, and in MTMR3 (rs9983, chromosome 22) in Pulpitis." (PMID 40701953, 2025).
astrocytic tumor (1 paper, 2015). A glial tumor of the brain or spinal cord showing astrocytic differentiation. "We found that hnRNPK was highly expressed in normal brain and its expression was lower in astrocytic tumors in a tumor grade manner and in an inverse pattern to that of RTVP-1." (PMID 26305187, 2015). "We found that hnRNPK was highly expressed in normal brain and its expression was decreased in astrocytic tumors in a tumor grade-dependent manner which is an inverse pattern to that of RTVP-1." (PMID 26305187, 2015). "Interestingly, hnRNPK expression was higher in oligodendroglioma compared with astrocytic tumors." (PMID 26305187, 2015).
bone marrow failure (1 paper, 2025). "Patients with ribosomopathies that cause bone marrow failure overexpress HNRNPK." (PMID 40338663, 2025). "Finally, we aimed to analyze the expression of HNRNPK in different ribosomopathies leading to bone marrow failure." (PMID 40338663, 2025).
bowel cancer (1 paper, 2025). "For example, the lncRNA CRLM1 has been implicated in bowel cancer metastasis, with its regulation of heterogeneous nuclear ribonucleoprotein K (hnRNPK) shown to slow tumour growth and reduce metastasis." (PMID 40490947, 2025).
developmental delay (1 paper, 2025). "Pathogenic variants in HNRNPK are associated with AUKS (OMIM #16580), a rare multisystem disorder characterized by developmental delay, congenital anomalies, and distinctive craniofacial features." (PMID 41216287, 2025).
Growth delay (1 paper, 2021). A deficiency or slowing down of growth pre- and postnatally. "A subset of probands have growth delay (30.5%, n = 61/200), particularly probands with variation in HNRNPH1 (62.5%, n = 5/8), HNRNPH2 (47.8%, n = 11/23), HNRNPR (90%, n = 9/10, significantly more so than HNRNPK probands [p = 0.03]), and HNRNPUL2 (50%, n = 3/6)." (PMID 33874999, 2021).
Hyperglycemia (1 paper, 2017). An increased concentration of glucose in the blood. "Insulin normalized hyperglycemia, hypertension,oxidative stress, and renal injury; inhibited renal Nrf2 andangiotensinogen (Agt) gene expression; and upregulated heterogeneousnuclear ribonucleoprotein F and K (hnRNP F and hnRNPK) expression in Akita mice with T1D." (PMID 28324005, 2017).
lung small cell carcinoma (1 paper, 2025). "This binding impedes the interaction of hnRNPK with MYC DNA and MYC mRNA, consequently inhibiting MYC transcription and translation, thereby playing a role in the progression of lung small cell carcinoma (NSCLC) via the hnRNPK-MYC-CDC25A pathway." (PMID 41235096, 2025).
metastatic disease (1 paper, 2021). "Taken together, these limited clinical cohort studies conducted using independent methods suggest a potential role for EV hnRNPK in metastatic disease." (PMID 33931969, 2021).
migraine (1 paper, 2023). "We also identified two additional genes, HNRNPK and PACSIN3, in the PWAS by integrating proteomics data from the Banner Sun Health Research Institute with migraine GWAS data." (PMID 37592229, 2023).
Miosis (1 paper, 2022). Abnormal (non-physiological) constriction of the pupil. "Transcriptomic analysis indicated that the germ cell-specific deficiency of hnRNPK caused the down-regulation of several miosis-related genes, supporting that hnRNPK might play a crucial role in meiotic regulation during spermatogenesis." (PMID 35455958, 2022).
muscle disorders (1 paper, 2026). "We also discuss the potential of hnRNPK as a diagnostic biomarker and therapeutic target in muscle disorders, and outline key directions for future research to resolve outstanding questions about its complex regulatory functions." (PMID 42165226, 2026).
myeloproliferative neoplasm (1 paper, 2021). A clonal hematopoietic stem cell disorder, characterized by proliferation in the bone marrow of one or more of the myeloid (i.e., granulocytic, erythroid, megakaryocytic, and mast cell) lineages. "Knockdown of HNRNPK promoted tumor growth of myeloproliferative neoplasm in vivo." (PMID 34295818, 2021).
Noonan syndrome (1 paper, 2025). Noonan Syndrome (NS) is characterized by short stature, typical facial dysmorphism and congenital heart defects. "HNRNPK is a key regulator of genes involved in diverse processes, including extracellular matrix (ECM) composition and potentially lymphatic development-pathways implicated in nuchal edema formation in other syndromes like Noonan syndrome." (PMID 41216287, 2025).
osteoporosis (1 paper, 2023). A condition of reduced bone mass, with decreased cortical thickness and a decrease in the number and size of the trabeculae of cancellous bone (but normal chemical composition), resulting in increased fracture incidence. "It is possible that increased hnRNPK in osteoblasts from Prdx5Ko can reduce AR expression levels, leading to osteoporosis in Prdx5Ko mice." (PMID 36735291, 2023).
ovarian carcinoma (1 paper, 2023). A malignant neoplasm originating from the surface ovarian epithelium. "Transwell assays demonstrated that hnRNPK deficiency inhibited the migratory and invasive abilities of ovarian cancer cells." (PMID 37639158, 2023). "The hnRNPK deficiency repressed ovarian cancer cell growth as determined by CCK-8 assays and inhibited the colony formation abilities of ovarian cancer cells." (PMID 37639158, 2023). "The suppressive effect of GAS5 on migration and invasion in ovarian cancer cells was reversed by overexpression of hnRNPK by transwell assays." (PMID 37639158, 2023). "High hnRNPK expression was significantly associated with poor overall survival (OS) and progression-free survival (PFS) of ovarian cancer patients." (PMID 37639158, 2023). "The results showed that hnRNPK was significantly upregulated in ovarian cancer compared with normal ovarian tissues." (PMID 37639158, 2023). "Our study showed one of the mechanisms that GAS5 inhibited ovarian cancer metastasis by down-regulating hnRNPK expression, and GAS5 can be used to predict the prognosis of ovarian cancer patients." (PMID 37639158, 2023). "In terms of mechanism, the research results showed that GAS5 affected the protein stability of hnRNPK, and then affected the occurrence and development of ovarian cancer." (PMID 37639158, 2023). "In summary, the finding of this study illustrates the vital function of GAS5-mediated hnRNPK protein stability in ovarian cancer." (PMID 37639158, 2023). "Together, these functional studies illustrated that hnRNPK exerted a tumor-promoting property in ovarian cancer cells." (PMID 37639158, 2023). "Our study enriches the molecular mechanism of GAS5 and regulates ovarian cancer progression via hnRNPK, which provided a novel therapeutic strategy to treat ovarian cancer." (PMID 37639158, 2023). "The hnRNPK promoted ovarian cancer development by cell function assays." (PMID 37639158, 2023). "Meanwhile, we analyzed hnRNPK expression in ovarian cancer using the GEO database." (PMID 37639158, 2023). "In our research, hnRNPK facilitated the growth and proliferation of ovarian cancer." (PMID 37639158, 2023). "Furthermore, rescue assays demonstrated hnRNPK was significantly involved in the progression of ovarian cancer." (PMID 37639158, 2023). "We speculated that GAS5 inhibited the stabilization of hnRNPK protein which impacted the expression of hnRNPK and the development of ovarian cancer due to the exon 12 of GAS5." (PMID 37639158, 2023). "When ovarian cancer cells were transfected with the GAS5 plasmids, Western blotting verified that hnRNPK protein was downregulated and the RNA expression of hnRNPK was no significant change by RT-qPCR." (PMID 37639158, 2023).
prostate adenocarcinoma (1 paper, 2021). "To detect HnRNPK protein levels in PrCa, we first performed IHC analysis on 22 primary prostate adenocarcinomas." (PMID 34857003, 2021).
schizophrenia (1 paper, 2019). A major psychotic disorder characterized by abnormalities in the perception or expression of reality. "We also found altered levels of hnRNPC, hnRNPK and hnRNPU in post mortem samples of the anterior temporal lobe (ATL) from patients with schizophrenia." (PMID 30890939, 2019).
spinal muscular atrophy (1 paper, 2019). A motor neuron disease that affect the muscles, and characterized by muscle weakness and atrophy resulting from progressive degeneration and irreversible loss of the anterior horn cells in the spinal cord (i.e., lower motor neurons) and the brain stem nuclei. "In addition, we surveyed the LC domains of other members in the hnRNP family, including hnRNPA2, hnRNPDL, hnRNPH, hnRNPK, and hnRNPR, which were identified to be closely associated with different diseases, such as ALS, spinal muscular atrophy (SMA), and cancer." (PMID 31043593, 2019).